CYP1A2 (cytochrome P450 family 1 subfamily A member 2)
Diseases named in the same sentence as CYP1A2 in open-access papers (continued):
Sharing a sentence is not in itself a finding about the gene and the disease.
cancer (69 papers, 2005 to 2026). A tumor composed of atypical neoplastic, often pleomorphic cells that invade other tissues. "Individuals with slow acetylator N-acetyltransferase 2 genotypes or CYP1A2 had elevated cancer risk with dye use." (PMID 41399670, 2026). "Researchers are now integrating genetic data into studies of diet and cancer; for example, incorporating CYP1A2 genotype strengthened the observed association of coffee with improved survival in colorectal cancer patients." (PMID 40650030, 2025). "Elevated in vivo expression of CYP1A2 has been postulated as a risk factor for cancers affecting the bladder, colon, and rectum, where exposure to substances like aromatic amines and heterocyclic amines (HAs) has been implicated in the etiology of the disease." (PMID 39039510, 2024). "In the comprehensive meta-analysis of available data, a significant association between the CYP1A2-163 C/A polymorphism and cancer risk was discerned." (PMID 39039510, 2024). "The CYP1A2 gene has been reported to house more than 40 single nucleotide polymorphisms, underscoring its potential role in the etiological risk of cancer." (PMID 39039510, 2024). "It has been demonstrated that sulforaphane inhibits the activity of CYP1A1 and CYP1A2 induced by compounds causing cancer, upregulates phase II enzymes like GSTs, and plays an inducing role in enzyme activities when added to the diet." (PMID 39148948, 2024). "The metformin treatment profiles reflect significant differences in branched chain amino acid catabolism, CYP1A2 activity, phosphatidylcholines and phospholipid metabolism, and lipid desaturase activity that are linked to cancer-promoting pathways." (PMID 36581893, 2022). "Polymorphisms in the CYP1A2 gene have already been correlated with cancer risk in liver, lung, stomach, pancreas, breast, endometrium and ovarian." (PMID 28404946, 2017). "Polymorphisms in the CYP1A2 gene have already been related with cancer risk in liver, lung, stomach, pancreas, breast, endometrium and ovarian." (PMID 28404946, 2017). "High in vivo CYP1A2 activity has been suggested to be a susceptibility factor for cancers of the bladder, colon and rectum, where exposure to compounds such as aromatic amines and HAs has been implicated in the etiology of the disease." (PMID 26865042, 2016). "Eleven GWASs on the association between CYP1A2 SNPs and cancer risk were identified after detail search of GWAS online databases." (PMID 26865042, 2016). "With these comprehensive meta-analyses, we aimed to provide a quantitative assessment of the association between the published genetic association studies on CYP1A2 single nucleotide polymorphisms (SNPs) and the risk of cancer." (PMID 26865042, 2016). "Several previous meta-analyses have been reported on the association between CYP1A2 gene polymorphisms and risk of cancer." (PMID 26865042, 2016). "We further examined the association between the CYP1A2 polymorphism and cancer risk according to ethnicity, source of controls and sample size and then stratified by cancer type." (PMID 26865042, 2016). "After data extraction, we calculated Odds Ratios (ORs) and 95 % confidence intervals (CIs) for the association between the retrieved CYP1A2 SNPs and cancer." (PMID 26865042, 2016). "Secondly, in our analyses, we included more studies than any previously published meta-analysis on the association between CYP1A2 polymorphism and cancer risks and investigated 6 different CYP1A2 SNPs." (PMID 26865042, 2016). "To clarify the potential contribution of CYP1A2 rs762551 to cancer risk, we performed a meta-analysis of the published case–control studies." (PMID 23157985, 2012). "Procarcinogen activation by CYP1A2 has one of the most serious effects on an individual’s susceptibility to cancer." (PMID 22864238, 2012). "We found that the carriers of CYP1A2 rs762551 C allele had a weak effect on the overall cancer risk in allele genetic model and in the dominant genetic model." (PMID 23157985, 2012).
cancer (continued). "The expression and activity of CYP1A2 has been demonstrated to relate to the risk of various cancers." (PMID 23157985, 2012). "Based on 19 studies providing data on CYP1A2 rs762551 polymorphism and cancer risk, we conduced a meta-analysis involving in 8218 cancer cases and 11165 controls to indicate if the rs762551 polymorphism was significantly associated with risk of cancer." (PMID 23157985, 2012). "In this meta-analysis, we evaluated the association of CYP1A2 rs762551 polymorphism with cancer risk in different genetic models (CC versus AA model, dominant model and recessive model)." (PMID 23157985, 2012). "In summary, our meta-analysis demonstrated a weak association of CYP1A2 rs762551 polymorphism with cancer risk, mainly in Caucasian population." (PMID 23157985, 2012). "Implications of CYP1A1 and CYP1A2 polymorphisms (mainly single-nucleotide polymorphisms—SNPs) have been extensively studied and provide insights into the cancer pathogenesis, risk stratification, response to therapy, and potential therapeutic targets for individuals with specific CYP1A genotypes." (PMID 41516250, 2025). "In general, the role of CYP1A2 polymorphisms in cancer development remains a subject of debate." (PMID 38433141, 2024). "Taking into account the predominant role of CYP1A2 in activation of toxic xenobiotics compared to its metabolism of prescription drugs, there are many epidemiological reports examining the role of CYP1A2 variants, metabolism of procarcinogens and cancer risk." (PMID 34564652, 2021). "Therefore, with these meta-analyses we aimed to provide a quantitative assessment of the association between all CYP1A2 polymorphisms and risk of cancer at various sites." (PMID 26865042, 2016). "The influence of the different CYP1A2 SNPs might be camouflaged by the presence of some yet unidentified causal genes involved in many other types of cancer." (PMID 26865042, 2016). "Our meta-analysis may be the most comprehensive meta-analysis of the relationship between the CYP1A2 rs762551 polymorphisms and the risk of cancer, to date." (PMID 26865042, 2016). "Considering the role of CYP1A2 in defending against environmental carcinogens and in the development of cancers, we performed a systematic meta-analysis from all eligible studies to address the overall risk of CYP1A2 variants in the development of all cancers involved." (PMID 23157985, 2012). "These polymorphisms may be related to altered inducibility of CYP1A2 expression by environmental chemicals and consequently influence the individual susceptibility to certain cancer." (PMID 23157985, 2012). "Furthermore, it is imperative to consider other genomic variations that may contribute to inter-individual differences in CYP1A2 expression, underscoring the complexity of comprehending the role of CYP1A2 in cancer susceptibility." (PMID 39039510, 2024). "Since CYP1A2 is one of the main hepatic CYPs involved in the bioactivation of carcinogens and metabolism of clinically used drugs, SNPs of this enzyme could affect cancer susceptibility or drug efficiency." (PMID 33654112, 2021). "The CYP1A2 polymorphism may prove to be useful for assessing cancer risk." (PMID 23157985, 2012). "Although the health implications in humans remain uncertain, CYP1A2 is involved in the metabolic activation of some carcinogens, and consequently, individual differences may reflect susceptibility to environmentally related cancer risk." (PMID 15743714, 2005). "Caffeine is primarily metabolized by cytochrome P450 enzymes, particularly CYP1A2, whose activity is suppressed in various cancers." (PMID 41142631, 2025). "Bioinformatic analysis also confirms that one of the top acetaminophen targets interacting with cancer-related genes is the sequences that encode members of the cytochrome P450 superfamily of enzymes (CYP3A4, CYP1A1, CYP1A2)." (PMID 41516250, 2025).
cancer (continued). "To date, over 30 SNPs have been identified in the CYP1A2 upstream sequence and its intron-1 region, contributing to its role in cancer development and progression." (PMID 38433141, 2024). "Genetic variations within the CYP1A2 gene are recognized to have multifaceted implications for cancer development." (PMID 39039510, 2024). "It has been indicated that high in vivo CYP1A2 activity could be related with a higher cancer risk on the basis that exposure to xenobiotics increases the activity of this enzyme and because some xenobiotics have been found to be involved in the aetiology of several types of cancers." (PMID 39769089, 2024). "Therefore, the substances that induce CYP1A2 may increase the risk of cancer development." (PMID 37049902, 2023). "The CYP family is well known for its responsibility in the metabolism of various drugs; therefore, considerable attentions have been directed to the pharmacokinetics and pharmacodynamics of CYP1A2 in cancers." (PMID 33500715, 2021). "The metabolic genes, CYP1A1 and CYP1A2, were widely underexpressed in multiple cancer types, whereas CYP1B1 exhibited different alterations in expression patterns." (PMID 33842355, 2021). "Strikingly, CALM1 was significantly underexpressed in all cancer types except for PAAD, whereas CYP1A2 was underexpressed in eight cancer types (e.g., BRCA and LIHC)." (PMID 33842355, 2021). "In our study, CYP1A2 was significantly differentially hypomethylated in five types of cancer, which was significantly differentially underexpressed in four of them." (PMID 33842355, 2021). "This analysis showed that each of these cancer types has a distinct pattern of expression for CYP1A2, CYP2B6, and CYP2C19." (PMID 31258835, 2019). "Thus, differences in CYP1A2 activity may influence individual susceptibility to cancer risk." (PMID 28404946, 2017). "The correlation between CYP1A2 overexpression and better event-free survival, probably is due to doxorubicin toxicity mediated by CYP1A2 enzyme against OS cancer cells, since CYP1A2 metabolizes this chemotherapy drug." (PMID 28404946, 2017). "Dietary flavonoids are important contributors for cancer prevention, due to their inhibition of CYP1A2 activity." (PMID 25061471, 2014). "Flavonoids are known to act as inhibitors of CYP1A1 and CYP1A2 resulting in prevention of cancer by environmental carcinogens." (PMID 22864238, 2012). "Studies have shown that the inhibition of CYP1A2 activity has been reported in various cancers, which may result in abnormal accumulation or excessive consumption of caffeine and its metabolites, such as theobromine." (PMID 41142631, 2025). "In addition, several studies have confirmed that CYP1A2 also possesses a certain metabolic capacity for AAI; by inducing the expression of CYP1A2, the formation of carcinogenic AAI–DNA adducts can be inhibited, thereby reducing the risk of cancer development." (PMID 40864066, 2025). "The pathway is a known mediator of fibrosis and suppressor of vascular invasion via cancer-associated fibroblasts (CAFs), potentially providing this subgroup with a more immunoprotected microenvironment.CYP2B6, CYP1A2, and CYP3A4 were associated with the “Chemical carcinogenesis” pathway." (PMID 40349011, 2025). "Multiple GWAS analyses showed genetic associations between CYP1A2 and CYP2A6 and cancer." (PMID 39457450, 2024). "However, CYP1A2 was significantly differentially hypomethylated in five cancer types, which was inconsistent with its transcriptional alterations." (PMID 33842355, 2021). "For instance, CYPs (e.g., CYP1A2) catalyze 2-hydroxylation of estradiol in which the product (i.e., 2-methoxyestradiol) inhibits cancer cell proliferation, suggesting reduced CYP1A2 activity due to PhIP exposure may trigger carcinogenesis." (PMID 32927802, 2020). "Meanwhile, CYP1A2 can also metabolically activate some known procarcinogens to the corresponding carcinogens, and thus has a significant effect on human tobacco-related cancers." (PMID 31366067, 2019).
cancer (continued). "According to two different meta-analyses, the CYP1A2 SNP rs762551 was associated with cancer susceptibility in the Caucasian but not the Asian or mixed populations." (PMID 31477036, 2019). "To date, there are no references to the associations between CYP1A2 rs12333983 and clinicopathological characteristics and prognosis of any cancer." (PMID 28418906, 2017). "In our meta-analyses, we showed that none of the investigated CYP1A2 polymorphisms were significantly associated with overall risk of cancer at various sites." (PMID 26865042, 2016). "In addition, induction of CYP1A2 promoter activity indicated that the repression of CYP1A2 expression in cancer cells is reversible, providing potential options for pharmacological interventions to correct this pathological disturbance." (PMID 27093553, 2016). "When the meta-analyses were performed excluding small sample size studies for all examined SNPs, there were still no significant results obtained for the association between CYP1A2 SNPs and cancer risk." (PMID 26865042, 2016). "Genetic polymorphism (rs762551A>C) in gene encoding cytochrome P450 1A2 (CYP1A2) has been shown to influence the inducibility of CYP1A2 expression and thus might be associated with risk of several types of human cancer." (PMID 23157985, 2012). "Inhibition of CYP1A2 can have major implications on cancer prevention." (PMID 22864238, 2012). "Other genes such as CYP3A4, CYP2C9, ADH4, ADH1A, and CYP1A2 enriched in the cytochrome P450 pathway are observed as metabolically active procarcinogens to genotoxic intermediates, and an association has been found between CYP enzyme activity and the risk to develop several forms of cancer." (PMID 31024618, 2019). "The differential expression patterns and drug sensitivity profiles of CYP1A2, AURKA, and ESR1 highlight their potential significance in the context of immune modulation and cancer therapy." (PMID 40864066, 2025). "Apart from CYP1A2 and ADORA2A, other genetic factors can influence CAF’s role in cancer and immunity." (PMID 40650030, 2025). "The activation of transcription factors such as aryl hydrocarbon receptor (AhR) and pregnane X receptor (PXR), which regulate the CYP450 enzymes (CYP1A2, CYP1A2, and CYP3A4), can further induce immunosuppression, cancer, and alter drug toxicity." (PMID 39456567, 2024). "Conversely, some CYP450 enzymes, like CYP1A1, CYP1A2, CYP1B1, CYP2A6, and CYP2E1, have a role in the onset and development of many cancers by converting pro-carcinogenic substrates into carcinogens." (PMID 39062040, 2024). "L-02 cells are normal human hepatocytes that also exhibit CYP1A2 and CYP3A4 expression and can be used as control cells to compare to cancer cells." (PMID 34031539, 2021). "It is well described that CYP1A1, CYP1A2, and CYP1B1 play an important role in the detoxication of environmental carcinogens and in the metabolic activation of dietary compounds with cancer preventive activity." (PMID 33219472, 2021). "These qPCR results confirmed a similar distribution of gene expression; overexpression of CYP1B1, CYP7A1, CYP17A1, and CYP19A1, and repression of CYP1A2, CYP2B6, CYP2C19, and CYP26A1 was observed in cancer tissues." (PMID 31258835, 2019). "Because of demonstrated unequivocal involvement in smoking-induced cancer in laboratory animals, four candidate genes––AHR, CYP1A1, CYP1A2, and CYP1B1––were selected for a clinical genotype-phenotype association study of HNSCC risk in smokers." (PMID 27894333, 2016). "In this work we demonstrated that a biosensor based on cytochrome P450 (CYP1A2, CYP2B6 and CYP3A4) and carbon-nanotubes enable the identification of different anti-cancer drugs, thus providing an innovative solution for point-of-care drug monitoring." (PMID 22778656, 2012). "Aside from CYP1A2 and CYP2A6, no significant cancer associations were found for the other phase I and phase II enzymes examined in this study." (PMID 39457450, 2024).
cancer (continued). "In contrast, some melatonergic genes were significantly overexpressed during cancer progression and were opposite to their differentially expressed status between cancerous and normal samples (e.g., RORB in COAD, KIRC, and STAD; CALM1 in BRCA; CYP1A2 in LUSC)." (PMID 33842355, 2021). "A genome-wide gene-expression profile of resected cancer tissue and the surrounding noncancerous liver tissue showed that the increased expression of the cytochrome P450 1A2 (CYP1A2) gene in noncancerous tissue was a predictive marker for non-recurrence." (PMID 32481552, 2020). "In addition, CYP1A2 and CYP2E1 were involved in the metabolic activation of various cancer ogenic substances and protoxins." (PMID 29534510, 2018). "A series of genes (e.g. CYP1A2, CYP3A4, CYP19A1), related to cancer in Cytochrome P450 Family, were down-regulated, with the exception of CYP2E1, which was up-regulated and may be involved in carcinogenic process of cervical cancer." (PMID 28225065, 2017). "In conclusion, the present data suggested that fucoxanthin inhibits CYP1A1, CYP1A2 and CYP3A4 enzyme activity and that these inhibitory effects may contribute towards the cancer preventive action of fucoxanthin." (PMID 24137426, 2013). "Cytochromes CYP1A1, CYP1A2, and CYP1B1, the members of the cytochrome P450 family 1, catalyze the metabolism of endogenous compounds, drugs, and non-drug xenobiotics which include substances involved in the process of carcinogenesis, cancer chemoprevention, and therapy." (PMID 37511239, 2023). "Notably, reports showed that Sal B could inhibit CYP1A2 and CYP3A4 mRNA expression and induce GST protein expression, indicating that Sal B may be a protective compound against cancer." (PMID 23662152, 2013). "Although not justifiable in itself as a therapeutic strategy, the status of apigenin as an inhibitor of CYP1A2, CYP2C9 and CYP3A4 means that it may enhance rather than inhibit the action of certain cancer medications by altering their pharmacokinetics in a beneficial way." (PMID 34084146, 2021).